RASGEF1C (RasGEF domain family member 1C)
Description:
Guanine nucleotide exchange factor (GEF).
Synonyms: FLJ35841
Tractability: Antibody: its Gene Ontology location is reachable by antibodies, with medium confidence.
Gene: Protein-coding gene on chromosome 5 (180,100,795 to 180,209,225, reverse strand). Ensembl gene ENSG00000146090.
Subcellular location (Human Protein Atlas): Mitochondria
Gene Ontology:
Molecular function: guanyl-nucleotide exchange factor activity
Biological process: Ras protein signal transduction; small GTPase-mediated signal transduction
Cellular component: plasma membrane
Genetic constraint (gnomAD): Loss-of-function variants: 22 observed, 51.03 expected, observed/expected ratio (o/e) 0.43, 90% interval 0.31 to 0.62. The upper end of that interval is the gene's LOEUF score, 0.62, which puts it in group 2 of 6, group 1 being the genes least tolerant of losing a copy. Missense variants: 479 observed, 572.28 expected, observed/expected ratio (o/e) 0.84, 90% interval 0.78 to 0.9. Synonymous variants: 237 observed, 237.72 expected, observed/expected ratio (o/e) 1, 90% interval 0.9 to 1.11.
Homologues: Orthologues: pig RASGEF1C (96% identical), rat Rasgef1c (95% identical), mouse Rasgef1c (95% identical), rabbit RASGEF1C (95% identical), dog RASGEF1C (94% identical), chimpanzee RASGEF1C (91% identical), macaque RASGEF1C (85% identical). Paralogues in human: RASGEF1B (69% identical), RASGEF1A (55% identical), RALGDS (22% identical), RAPGEF2 (22% identical), RAPGEF3 (22% identical), RAPGEF5 (21% identical), RASGRF1 (21% identical), RASGRF2 (21% identical), RAPGEF6 (21% identical), RGL1 (20% identical), RGL3 (20% identical), RAPGEF1 (20% identical), and 12 more.
Diseases named in the same sentence as RASGEF1C in open-access papers:
RASGEF1C is named in the same sentence as 1 disease in open-access papers, as found by Europe PMC text mining. Sharing a sentence is not in itself a finding about the gene and the disease. The quoted sentences say what the papers report.
Alzheimer disease (1 paper, 2021). A progressive, neurodegenerative disease characterized by loss of function and death of nerve cells in several areas of the brain leading to loss of cognitive function such as memory and language. "Expression dysregulation of the neuron-specific gene, RASGEF1C (RasGEF Domain Family Member 1C), occurs in late-onset neurocognitive disorders (NCDs), such as Alzheimer’s disease." (PMID 34584172, 2021).